HUWE1 (HECT, UBA and WWE domain containing E3 ubiquitin protein ligase 1)
Description:
E3 ubiquitin-protein ligase which mediates ubiquitination and subsequent proteasomal degradation of target proteins. Regulates apoptosis by catalyzing the polyubiquitination and degradation of MCL1. Mediates monoubiquitination of DNA polymerase beta (POLB) at 'Lys-41', 'Lys-61' and 'Lys-81', thereby playing a role in base-excision repair. Ubiquitinates MFN2 to negatively regulate mitochondrial fusion in response to decreased stearoylation of TFRC. Ubiquitination of MFN2 also takes place following induction of mitophagy; AMBRA1 acts as a cofactor for HUWE1-mediated ubiquitination. Regulates neural differentiation and proliferation by catalyzing the polyubiquitination and degradation of MYCN. May regulate abundance of CDC6 after DNA damage by polyubiquitinating and targeting CDC6 to degradation. Mediates polyubiquitination of isoform 2 of PA2G4. Acts in concert with MYCBP2 to regulate the circadian clock gene expression by promoting the lithium-induced ubiquitination and degradation of NR1D1. Binds to an upstream initiator-like sequence in the preprodynorphin gene (By similarity). Mediates HAPSTR1 degradation, but is also a required cofactor in the pathway by which HAPSTR1 governs stress signaling. Acts as a regulator of the JNK and NF-kappa-B signaling pathways by mediating assembly of heterotypic 'Lys-63'-/'Lys-48'-linked branched ubiquitin chains that are then recognized by TAB2: HUWE1 mediates branching of 'Lys-48'-linked chains of substrates initially modified with 'Lys-63'-linked conjugates by TRAF6. 'Lys-63'-/'Lys-48'-linked branched ubiquitin chains protect 'Lys-63'-linkages from CYLD deubiquitination. Ubiquitinates PPARA in hepatocytes (By similarity).
Synonyms: ARF-BP1; HectH9; LASU1; Mule; URE-B1; KIAA0312; UREB1; HSPC272; Ib772; MRXST
Tractability: Small molecule: a structure with a bound ligand is known; it has a high-quality binding pocket. Antibody: its Gene Ontology location is reachable by antibodies, with high confidence. PROTAC: ubiquitination databases record sites on it; its protein half-life has been measured.
Target class: Enzyme; Transferase
Gene: Protein-coding gene on chromosome X (53,532,096 to 53,686,752, reverse strand). Ensembl gene ENSG00000086758.
Subcellular location: Cytoplasm; Nucleus; Mitochondrion
Subcellular location (Human Protein Atlas): Cytosol; Nucleoplasm; End piece; Mid piece; Nuclear membrane; Principal piece
Pathways (Reactome):
Immune System: Antigen processing: Ubiquitination & Proteasome degradation; Neutrophil degranulation
Gene Ontology:
Molecular function: histone ubiquitin ligase activity; protein binding; RNA binding; ubiquitin protein ligase activity; ubiquitin-protein transferase activity; ubiquitin-ubiquitin ligase activity; DNA binding
Biological process: base-excision repair; circadian regulation of gene expression; negative regulation of mitochondrial fusion; positive regulation of canonical NF-kappaB signal transduction; positive regulation of establishment of protein localization to mitochondrion; positive regulation of protein ubiquitination; positive regulation of type 2 mitophagy; protein branched polyubiquitination; protein K48-linked ubiquitination; protein monoubiquitination; protein polyubiquitination; Golgi organization; membrane fusion; negative regulation of peroxisome proliferator activated receptor signaling pathway; proteasome-mediated ubiquitin-dependent protein catabolic process; ubiquitin-dependent protein catabolic process; chromatin remodeling; protein ubiquitination
Cellular component: cytoplasm; cytosol; extracellular exosome; membrane; mitochondrion; nuclear membrane; nucleoplasm; nucleus; extracellular region; ficolin-1-rich granule lumen; Golgi membrane; secretory granule lumen
Gene-disease validity (ClinGen):
ClinGen rates the evidence that HUWE1 causes each of these diseases.
non-syndromic X-linked intellectual disability (X-linked): Definitive.
Homologues: Orthologues: macaque HUWE1 (99% identical), pig HUWE1 (99% identical), chimpanzee HUWE1 (99% identical), dog HUWE1 (98% identical), mouse Huwe1 (98% identical), rat Huwe1 (98% identical), rabbit HUWE1 (97% identical), guinea pig HUWE1 (97% identical), tropical clawed frog huwe1 (87% identical), zebrafish huwe1 (79% identical), Drosophila melanogaster HUWE1 (38% identical), Caenorhabditis elegans eel-1 (29% identical). Paralogues in human: WWP1 (8% identical), HECW1 (7% identical), HECW2 (7% identical), NEDD4L (7% identical), UBR5 (7% identical), ITCH (7% identical), WWP2 (7% identical), HECTD4 (7% identical), SMURF2 (7% identical), NEDD4 (6% identical), SMURF1 (6% identical), HERC2 (6% identical), and 12 more.
Diseases named in the same sentence as HUWE1 in open-access papers:
HUWE1 is named in the same sentence as 104 diseases in open-access papers, as found by Europe PMC text mining. Sharing a sentence is not in itself a finding about the gene and the disease. The quoted sentences say what the papers report.
breast carcinoma (14 papers, 2006 to 2026). "Numerous E3 ubiquitin ligases, such as cIAP2, FBW7, RNF126, and HUWE1, have been documented to be associated with breast cancer tumorigenesis and drug resistance." (PMID 34650035, 2021). "Upon ionizing radiation or mitomycin treatment, knockdown of HUWE1 confers treatment resistance to breast cancer cells." (PMID 30176860, 2018). "Furthermore, MAGEE1 is frequently mutated and considered a candidate cancer gene in breast cancer, WWC3 has a high potential for complete or partial escape in ovarian cancer, and HUWE1 is known as a tumor suppressor gene." (PMID 41522471, 2026). "Further, TMUB1/STT3A/HUWE1 expression in breast cancer tumors was assessed using RT-qPCR." (PMID 36376293, 2022). "Knockdown of HUWE1 reduces Myc functions in breast cancer cell lines and co-depletion of HUWE1 and Mnt, an antagonist of transactivation by Myc further abolished the colony formation in HeLa cells, suggesting an oncogenic role of HUWE1 in regulating Myc functions." (PMID 30176860, 2018). "This approach identified 3 candidates: HUWE1 (from our MS data), and β-TRCP and DBC2 (previously reported to degrade MSI2 in gastric and breast cancer, respectively)." (PMID 41049614, 2025). "Recently, we demonstrated that HUWE1 plays an essential role in regulating the stability of BRCA1, a critical tumor suppressor involved in breast cancer tumorigenesis." (PMID 25883150, 2015). "In breast cancer cells that acquired resistance to lapatinib, MDM2 ubiquitinates another ubiquitin E3 ligase, HUWE1, which indirectly inhibits apoptosome activation by preventing HUWE1 from ubiquitinating MCL-1." (PMID 36694209, 2023).
lung carcinoma (13 papers, 2015 to 2026). "The authors revealed that high expression of HUWE1 was associated with poor survival in lung cancer patients." (PMID 35937685, 2022). "The E3 ubiquitin (Ub) ligase HUWE1 has been implicated in tumor formation, cell migration and invasion and is significantly overexpressed in a number of epithelial tumors, including lung carcinoma." (PMID 29221141, 2017). "Our current results on the negative regulation of EGFR stability through the cooperation of HUWE1 and JMJD5 provide further insight into the complex role of HUWE1 in lung cancer progression." (PMID 37813845, 2023). "Previous studied demonstrated HUWE1 played disparate role in different tumors, as an oncogene in liver cancer, lung cancer, colon adenocarcinoma, and stomach adenocarcinoma, whereas an antioncogene in skin tumors, and thyroid cancer." (PMID 37700273, 2023). "The expression levels of HUWE1 are frequently higher in certain cancers, such as lung cancer and leukemia, than in the corresponding normal tissues." (PMID 35937685, 2022). "For example, E3 ubiquitin-protein ligase (HUWE1) has been shown to promote cancer progression in lung cancer, gastric cancer and multiple myeloma, while tumor suppressive functions was also reported in prostate cancer and other cancer types." (PMID 35183197, 2022). "In lung carcinoma cells, aberrant HUWE1-mediated ubiquitylation has been shown to contribute to enhanced cell-cell adhesion disassembly, motility, and invasiveness." (PMID 29221141, 2017). "We show that in epithelial cells, including lung carcinoma cells, stimulated with HGF, TIAM1—a critical regulator of cadherin-associated adhesion— is rapidly targeted for proteasome-dependent degradation via HUWE1-mediated ubiquitylation." (PMID 25543140, 2015). "We also show that TIAM1 and HUWE1 protein levels are negatively correlated in early-stage lung cancer specimens, consistent with this regulatory mechanism operating in human tumors." (PMID 25543140, 2015). "Significantly, we show that HUWE1 stimulates human lung cancer cell invasion through regulating TIAM1 stability." (PMID 25543140, 2015). "Interestingly, overexpression of HUWE1 has been correlated to breast, brain, and prostate cancer progression, but also is down-regulated in both colorectal and lung cancer." (PMID 36111624, 2022). "HUWE1 contributes to lung tumorigenesis, and the mRNA expression of HUWE1 could be used to assess the prognosis of lung cancer patients." (PMID 35158999, 2022). "This indicates a critical role for HUWE1 in lung cancer dissemination." (PMID 25543140, 2015). "HUWE1 is significantly overexpressed in a number of epithelial tumors including lung carcinoma." (PMID 25543140, 2015). "Based on this evidence, we conclude that aberrant HUWE1-mediated ubiquitylation of TIAM1 could contribute to the enhanced invasiveness of lung carcinoma cells." (PMID 25543140, 2015). "Thus, HUWE1 appears essential for the invasion of lung carcinoma cells and this is entirely dependent on ubiquitylation of TIAM1." (PMID 25543140, 2015). "For instance, HUWE1 (HECT, UBA and WWE domain-containing E3 ubiquitin protein ligase 1) is frequently overexpressed in lung cancer, which correlates with poor prognosis." (PMID 40002221, 2025). "HUWE1 mediated the ubiquitination and degradation of the RAC activator TIAM1, which abolished cell-cell adhesion and promoted lung cancer cell invasion and dissemination." (PMID 35937685, 2022).
lung carcinoma (continued). "Several types of enzymes (e.g., HUWE1) and enzyme modulators (e.g., IQGAP) have been identified in lung cancer exosomes, thus implying that these proteins may be transferred from exosomes to target cells to perform their functions." (PMID 35158999, 2022). "demonstrate that the E3 ligase HUWE1 degrades the RAC activator TIAM1 following HGF stimulation, promoting cell junction disassembly, motility, and invasion in epithelial cells including lung cancer cells." (PMID 25543140, 2015). "Finally, we demonstrate that HUWE1 and TIAM1 protein levels are inversely correlated in human lung carcinomas." (PMID 25543140, 2015). "Here, we show that in response to HGF, HUWE1 ubiquitylates TIAM1 on lysine 595, triggering its proteasomal degradation predominantly at cell-cell adhesions, thereby enabling disassembly of cell junctions and induction of cell migration and invasion, including in lung carcinoma cells." (PMID 25543140, 2015).
Intellectual disability (11 papers, 2013 to 2025). "Another male patient carried a de novo hemizygous missense variant in HUWE1, presenting with microcephaly, epilepsy, severe intellectual disability, and marked ASD traits." (PMID 40558542, 2025). "For example, in the aged hippocampus, the X-chromosome gene Huwe1, encoding an E3 ubiquitin ligase linked to intellectual disability, was associated with an SE event that showed both a change with aging in females and a sex bias in the aged hippocampus." (PMID 38318533, 2024). "De novo heterozygous pathogenetic variant in HUWE-1 gene, associated with intellectual disability and epilepsy." (PMID 38671719, 2024). "A large body of literature has shown that HUWE1 copy number variations are linked with intellectual disability, and HUWE1 is considered a dosage-sensitive gene associated with this phenotype." (PMID 35937685, 2022). "Mutations in the human ortholog of EEL-1, called HUWE1, are associated with both syndromic and non-syndromic intellectual disability." (PMID 34797853, 2021). "Xp11.22 microduplication syndrome [OMIM #300705] is caused by duplication of HUWE1 and is characterized by mild to moderate intellectual disability." (PMID 28414775, 2017). "In addition, more HUWE1 missense mutations and splice site variants were reported in a large cohort of patients with intellectual disability harboring HUWE1 variants, including in 14 females and 7 males." (PMID 35937685, 2022). "Furthermore, Huwe1 gene is located on the X chromosome and associated with X chromosome-linked intellectual disability." (PMID 35937685, 2022). "There is reported evidence that both an increase and decrease in HUWE1 function can result in intellectual disability, increase hypersensitivity to oxidative stress, and affect genome stability." (PMID 34797853, 2021). "We recently reported that duplication of the E3 ubiquitin ligase HUWE1 results in intellectual disability (ID) in male patients." (PMID 24303071, 2013). "Overall, the function of HUWE1 in neural development is most likely to be promoting cell differentiation instead of proliferation, although how this function contributes to intellectual disability remains largely unknown." (PMID 35937685, 2022). "Intellectual disability is associated with a protein called HECT E3 ubiquitin ligase, HUWE1." (PMID 34797853, 2021). "Finally, we discuss extensive human genetic studies that strongly implicate HUWE1 in intellectual disability, and heighten the importance of continuing to unravel how Huwe1 affects the nervous system." (PMID 32336296, 2020). "Among the other tested genes, we found that three CD missense URVs in HUWE1, a gene primarily reported as an intellectual disability gene in literatures, are hemizygous (two maternally inherited variants and one DNM), providing additional evidence for association of this gene with EE/DEE." (PMID 31175295, 2019). "Duplications and deletions involving KDM5C, IQSEC2 and TSPYL2 that do not overlap with HUWE1, have also been shown to cause developmental delay, intellectual disability, behavioral disturbances and/or autistic features." (PMID 28414775, 2017). "Importantly, HUWE1 is the principal candidate gene responsible for non-syndromic X-linked intellectual disability caused by microduplication of Xp11.22 and patients possessing HUWE1 variants were found to exhibit severe intellectual disability." (PMID 31683805, 2019).
colon carcinoma (10 papers, 2014 to 2023). "This was further substantiated in an inducible, shRNA-mediated HUWE1 knockdown system established in the colon cancer cell line Ls174T." (PMID 28943312, 2017). "Together with our identification of HUWE1 mutations present in human CRC that perturb its ubiquitin ligase activity, this strongly suggests it is a bona fide colonic tumour suppressor gene." (PMID 28003334, 2017). "Collectively, the data establish that these compounds block MYC-dependent transcriptionalactivation via inhibition of HUWE1 in colon cancer cells." (PMID 25253726, 2014). "Here, we used bothshRNAs and small molecule inhibitors to explore the role of HUWE1 as a regulator of MYC function inhuman colon cancer cells." (PMID 25253726, 2014). "It islikely, therefore, that the high levels of ARF and HDAC2 enhance the potency of the HUWE1 inhibitorsin colon cancer cells and contribute to the specificity of the effects." (PMID 25253726, 2014). "Huwe1 is overexpressed in multiple human tumors, is essential for proliferation of a subset of tumors, and is required for activation of Myc-inducible target genes including ribosomal proteins in colon carcinoma cells." (PMID 27552055, 2016). "We concluded that HUWE1 isrequired for growth and tumor formation of human colon cancer cells." (PMID 25253726, 2014). "To test whether HUWE1 is required for growth of colon cancer cells in culture, we generatedretroviruses that constitutively express shRNAs targeting HUWE1." (PMID 25253726, 2014). "Unlike its role in colon cancer, our data thus do not imply HUWE1 as important regulator of MYC activity in MM." (PMID 33116152, 2020). "In contrast to colon carcinoma cells, HUWE1 is not required for proliferation ofembryonic stem (ES) cells and deletion of HUWE1 instead delays the decrease of N-MYC levels thatoccurs upon removal of leukemia inhibitory factor (LIF) from the medium (Zhaoet al, 2008)." (PMID 25253726, 2014). "We concluded that HUWE1 is requiredfor activation, but not repression, of MYC target genes in colon carcinoma cells." (PMID 25253726, 2014).